IL6 (interleukin 6)
Diseases named in the same sentence as IL6 in open-access papers (continued):
Sharing a sentence is not in itself a finding about the gene and the disease.
glioma (441 papers, 1999 to 2026). A benign or malignant brain and spinal cord tumor that arises from glial cells (astrocytes, oligodendrocytes, ependymal cells). "Heightened levels of IL-6 in the glioma TME have also been linked with enhanced tumor growth and apoptotic resistance." (PMID 41157253, 2025). "CCL2 is found to be expressed in glioma, which causes nearby microglia to produce IL-6, resulting in a more infiltrative tumor." (PMID 41157253, 2025). "Elevated IL6 levels have been linked to glioma growth, with hypoxia-induced IL6 secretion enhancing GBM autophagy; hence, targeted inhibition by tocilizumab can prevent GBM progression and autophagy." (PMID 40678806, 2025). "We constructed a univariate and multivariate cox regression analysis based on ICD-DEGs to identify three genes (FOXP3, MYD88 and IL6) associated with prognosis of glioma patients." (PMID 37456890, 2023). "In glioma, the elevated expression of IL-6 and its receptor is associated with poor patient survival." (PMID 35626018, 2022). "There is a large number of macrophages infiltration in the glioma microenvironment, which is associated with a variety of factors secreted by tumor cells, including IL-4, IL-6, IL-10, TGF-β, microRNAs, macrophage colony-stimulating factor (M-CSF), and CCL2." (PMID 36483052, 2022). "The glioma environment is subject to chronic inflammation, and IL-6 is one of the cytokines strongly associated with the chronic inflammatory phenotype often associated with GBM." (PMID 35626018, 2022). "A significant association was demonstrated between IL-6 mRNA levels and the grade of glioma malignancy." (PMID 35054779, 2022). "We also evaluated a possible correlation of sHLA-G with the level of immunoregulatory and anti-inflammatory cytokine IL-10, pro-inflammatory cytokine IL-6, and their ratio (IL-10/IL-6), and the association of sHLA-G with the survival of glioma patients." (PMID 35626255, 2022). "IL-6 expression increases with glioma malignancy grade and is associated with shorter survival of GBM patients." (PMID 34440820, 2021). "So we also substantiated a crucially positive correlation of the risk score with IL-1α, IL-1β, IL-6, IL-8, and IL-18 expression levels in patients with glioma." (PMID 34114970, 2021). "Their latest results indicate that the pro‐inflammatory cytokine expression of TNF, IL‐8, IL‐6 and NF‐κB is enhanced in glioma‐associated ECs." (PMID 33300633, 2021). "High or increasing levels of circulating IL-6 or YKL-40 have been associated with decreased survival of patients with glioma either alone or in combination with other biomarkers, although not consistently." (PMID 32363159, 2020). "Another study has provided data regarding molecular mechanisms underlying hypoxia-induced glioma cell autophagy, evidencing that the inhibition of IL6-Stat3 axis represses autophagy in glioblastoma cell lines in vitro." (PMID 31690341, 2019). "Consistently with these in vitro results, our in vivo study with an orthotopic, syngenetic GL26 glioma model indicated a remarked increase in IL-6 expression by tumor-associated ECs, in comparison to normal brain ECs." (PMID 29422647, 2018). "The expression levels of proinflammatory cytokines such as TNF-α and interleukin (IL)-6 in the inflamed brain and the blood of postsurgical U87 glioma-bearing mice were measured using commercial enzyme-linked immunosorbent assay (ELISA) kits." (PMID 30429468, 2018). "Consistently, we showed that GBM-associated ECs expressed IL-6 at a relatively higher level, compared with U251 glioma cells, T4123 glioma stem cells, and human PBMC monocytes." (PMID 29422647, 2018). "Together, these findings reveal that elevated IL6 signalling is associated with more aggressive subtypes of gliomas and contributes to poor patient outcome." (PMID 29258522, 2017). "Expression levels of IL-6 have also been inversely associated with glioma patient’s survival because of the role played in GBM growth." (PMID 28107450, 2017).
glioma (continued). "IL-6 is one of the most studied cytokines in gliomas and has been associated with tumor growth, angiogenesis, and poor survival." (PMID 26755664, 2016). "Gliomas contain high levels of inflammatory cytokines, namely IL-1β, IL-6, and IL-8, which are associated with increase invasion levels." (PMID 25596741, 2015). "The present study investigated the phosphorylation of specific residues of NFκB is association with TNF-α-stimulated IL-6 synthesis in C6 glioma cells." (PMID 20205746, 2010). "In gliomas, cytokines, such as interleukin (IL)-6 (IL-6) and epidermal growth factor, can cause subsequent phosphorylation and activation of STAT-3." (PMID 19900287, 2009). "•Interleukin-6 is a pro-inflammatory cytokine linked to the growth of gliomas." (PMID 39512605, 2024). "Additionally, tumor-associated astrocytes (TAAs) promote glioma invasion via signaling pathways including NF-κB, interleukin (IL)-6/JAK/STAT, and SHH signaling, facilitated by connexin 43 (Cx43)-mediated gap junction formation." (PMID 38732975, 2024). "The level of IL-6, one of the major Th17-promoting cytokines, was significantly elevated in GBM compared to low-grade gliomas, while a higher level of IL-6 in CSF was associated with high infiltration of tumor-associated macrophages and poor prognosis in patients with GBM." (PMID 38918274, 2024). "The immune microenvironment is composed of glioma-associated immune cells, such as microglia, macrophages, and B cells, and immunoregulatory factors, such as interleukin (IL)-6, IL-10, and transforming growth factor β (TGF-β), which regulate the progression of glioma." (PMID 35982954, 2022). "Namely, IL-6 has been associated with pro-tumorigenic role in gliomas." (PMID 35538218, 2022). "Furthermore, IL-6 induces Arg-1 expression on glioma associate macrophages, leading to T cell suppression." (PMID 36430641, 2022). "Therefore, the expression of IL‐8 and IL‐6 in the glioma‐associated ECs induced by TNF is blocked by the NF‐κB‐mediated pathway, which has important implications for anti‐angiogenesis therapy." (PMID 33300633, 2021). "IL-6 is abundantly produced by glioma cells and upregulation of IL-6 in gliomas is associated with the grade of malignancy and could play an important role in gliomagenesis, angiogenesis, and metastasis." (PMID 32878114, 2020). "As a result, secreted IL-6 could bind to the extracellular sIL-6R and then associate with membrane-bound gp130 to initiate intrinsic IL-6 signaling in glioma cells." (PMID 33227992, 2020). "IL-6 is also associated with decreased survival in resected glioma tissue, and may be a prognostic indicator for glioma patients." (PMID 33235296, 2020). "A total of 10 studies reported an association between IL‐6 and the pathogenesis of glioma." (PMID 31599129, 2019). "Glioma-associated microglia and macrophages release several cytokines and growth factors (interleukin (IL) IL-6, IL-1β, transforming growth factor-β (TGF-β)), epidermal growth factor (EGF), and stress-inducible protein 1 (STI1) that facilitate the tumor proliferation and migration." (PMID 28346397, 2017). "The strong association between IDH-wildtype gliomas and upregulation of IL6 and IL6R expression suggests that the IL6 signalling may contribute to the poor prognosis of patients with wild-type IDH1, although the exact mechanism requires further research." (PMID 29258522, 2017). "IL-6 is implicated as major regulators of glioma cell growth and invasiveness." (PMID 23688241, 2013). "A recent study demonstrated that CLCF1, an interleukin-6 (IL-6) family cytokine involved in neurodevelopment, regulates the tumor immune milieu and has potential as a prognostic marker and therapeutic target in patients with glioma associated with phosphatase and tensin homolog (PTEN) mutations." (PMID 40169936, 2025). "IL-6 values were significantly higher than in healthy controls and progressively increased with glioma grade 10." (PMID 39781345, 2025).
glioma (continued). "The IL6-JAK-STAT3 and TNF-α signaling pathways via NF-κB were associated with the inflammation in glioma." (PMID 38985240, 2025). "Glioma cells and infiltrating immune cells evade immune surveillance by secreting immunosuppressive factors, such as IL-6, IL-10, TGF-β, and prostaglandin E2, whose expression is regulated by tumor-derived growth factors." (PMID 41426972, 2025). "An investigation into glioma patients reported a positive correlation between serum soluble α-Klotho (sαKlotho) levels and IL-6 (p = 0.0347), along with other biomarkers such as VEGF, fractalkine, IFN-γ, GDNF, IL-4, and IL-13." (PMID 40426990, 2025). "The analysis of GSEA and GSVA revealed that the CNOT7 participated in the development of glioma via G2M checkpoint, E2F targets, IL6-JAK-STAT3, and TNF-α signaling pathways via NF-κB." (PMID 38985240, 2025). "Given that IL‐6 contributes to glioma immune escape, combinations that pair PD‐1/PD‐L1 inhibitors with IL‐6/STAT3 pathway modulators (or related JAK/STAT interventions) merit prospective testing to couple immune reinvigoration with inflammation dampening." (PMID 41354084, 2025). "Higher levels of IL-6 mRNA expression were observed in glioma samples from patients with advanced histopathological stages compared to those with lower stages." (PMID 40143164, 2025). "Both IL-6 and IL-8 also contribute to glioma growth by promoting angiogenesis, tumour proliferation and resistance to apoptosis." (PMID 41034696, 2025). "The results showed that NF-κB inhibitor BAY11–7082 significantly decreased the mRNA and protein expression levels of IL-6 in BV2 cells activated by CM from GL261 or ALTS1C1 glioma cells." (PMID 41367876, 2025). "Inflammatory and glioma cells express and can release SP that regulates neurogenic inflammation mediated by the release of IL-1β, IL-6, IL-8, TNF-α, GM-CSF, and LIF." (PMID 39941886, 2025). "In glioma, CNOT7 is overexpressed and associated with poor prognosis, contributing to glioma progression through TNF-α and IL6-JAK-STAT3 pathways." (PMID 41249119, 2025). "Numerous studies have demonstrated a link between IL-6 expression, glioma progression, and patient survival outcomes." (PMID 40143164, 2025). "In glioma, stem cells communicate with microglia via miRNA in extracellular vesicles, with miR-129-3p regulating IL-6, IL-8, and TNFα." (PMID 40248351, 2025). "We also investigated the effects of naringenin on modulating the inflammatory molecules IL-6, CCL2, and TNF-α associated with immunosuppression in glioma cells." (PMID 40149846, 2025). "Elevated expression of IL-6 and MMP14 are strongly associated with reduced survival rates, particularly in high-grade gliomas." (PMID 40345526, 2025). "SP and histamine also induce interleukin-6 expression by a mechanism involving PKC and nuclear factor-IL-6 in U-373 MG glioma cells." (PMID 39941886, 2025). "IL-6 can bind to IL-6R on the surface of glioma cells and activate the downstream JAK2/STAT3 signaling pathway, enabling them to acquire the stemness and invasiveness phenotype." (PMID 40243478, 2025). "Blocking IL-6 has been previously shown to suppress the growth of subcutaneously implanted human glioma stem cell-derived xenografts in immunocompromised mice." (PMID 40161763, 2025). "GBM cells release glycoprotein osteoponton (OPN), which is also known to induce invasion, survival, and angiogenesis but at the same time stimulates IL-6 production in microglia, which affects glioma cells by enhancing their invasiveness." (PMID 41157253, 2025). "STAT3 is turned on by signals including IL-6, IL-10, epidermal growth factor and fibroblast growth factor, making it a key player in glioma immune evasion." (PMID 41157253, 2025). "Other notable signals included IL6, VEGFA, TGFB1, and ANXA1, genes associated with mesenchymal transition, angiogenic niches, and poor prognosis in glioma." (PMID 41514565, 2025).
glioma (continued). "Remarkably, IL‐6 modulates glioma characteristics like blockade of sequelae like apoptosis, facilitation of survival, proliferation, angiogenesis, invasiveness, as well as metastasis." (PMID 41498028, 2025). "Paradoxically, IL-6 in the glioblastoma TIME can stimulate the growth of glioma stem cells and increases immunosuppressive cytokines that activate pro-tumor macrophages." (PMID 40161763, 2025). "The enrichment analysis revealed that the CNOT7 participated in the development of glioma via G2M checkpoint, E2F targets, IL6-JAK-STAT3, and TNF-α signaling pathways via NF-κB." (PMID 38985240, 2025). "In mouse models of non-CNS cancer, IL-6 blockade reduces the number of macrophages, myeloid cells, and Th17 cells and increases the number of effector T cells in the TIME, leading to therapeutic synergy when combined with ICI20." (PMID 40161763, 2025). "Intriguingly, in glioma-bearing rats, FTY720 can internalize CXCR4 on glioma-associated microglia and macrophages in the tumor microenvironment to suppress the migration/invasion of C6 glioma cells by preventing MAPK-mediated IL-6 release." (PMID 38894892, 2024). "In vitro experiments have shown that IL-6 and IL-8 produced by glioma cells prolong the lifespan of neutrophils, indicating that neutrophils and glioma cells interact reciprocally." (PMID 38779679, 2024). "Different signaling pathways have been suggested to play an important role in the proneural-to-mesenchymal subtype transition of gliomas including cytokines IL6, TGFβ, and TNFα." (PMID 38632238, 2024). "Compared with control-derived macrophages, glioma-derived TAMs produced higher levels of IL-6, IL-8, CCL2, and CCL8." (PMID 38370418, 2024). "Extracellular vesicles, isolated from glioma cells in hypoxic conditions, contained high levels of IL-6 and miR155-3p, promoting M2 macrophage polarization via the IL-6-pSTAT3-miR-155-3p-autophagy-pSTAT3 pathway and, consequently, glioma progression." (PMID 38794298, 2024). "Studies have found that glioma cells express many factors related to the proliferation of MDSCs (IL-6, IL-10, VEGF, PGE-2, GM-CSF, and TGF-β2); however, blocking the chemokine CCL2 signaling pathway in glioma cells effectively reduces the recruitment of MDSCs." (PMID 39206155, 2024). "The KEGG results suggested that TRIM56 played a role in the activation of PI3K-AKT pathway in glioma and “IL6-JAK-STAT3 signaling” gene set was enriched by GSEA analysis." (PMID 38348047, 2024). "The high-risk group displayed elevated expression levels of CA9, IL-2, and IL-6 in the glioma tissues." (PMID 39574472, 2024). "Studies have also shown that suppression of STOML2 reduces IL-6 expression in glioma by inhibiting the transcription of NF-κB." (PMID 38214751, 2024). "Glioma-derived exosomes enriched in IL-6 and miR-155-3p initiate autophagy and promote M2 polarization in TAMs through the IL-6-p-STAT3-miR-155-3p-autophagy-p-STAT3 positive feedback loop, enhancing glioma progression." (PMID 39430253, 2024). "The release of cytokines, including IL-12, IL-1B, CCL8, and IL-6 by TAMs, has also been shown to promote glioma stem cell renewal." (PMID 38254796, 2024). "Studies had shown that inhibiting of the IL-6/JAK2/STAT3 signaling pathway inhibited the proliferation of glioma cells and promotes apoptosis." (PMID 37642814, 2024). "To validate the findings obtained from the bioinformatic analysis, we conducted IHC assays for CA9 (a biomarker of hypoxia and glycolysis), IL-2, and IL-6 proteins in glioma tissues obtained from our research cohort." (PMID 39574472, 2024). "In vitro experiments have demonstrated that knockdown of TIM-1 expression inhibited the proliferation, migration, and invasion of glioma (U87, U251) cells and decreased the levels of TGF-β1, IL-6, IL-4, and IL-10 in gliomas." (PMID 38831760, 2024). "Human glioma cells induce microglia to secrete and release IL-6 through CCL2/CCR2 axis, thus promoting glioma invasion." (PMID 38229178, 2024).
glioma (continued). "M2-like macrophages drive glioma, angiogenic mimicry by amplifying IL-6 secretion in glioma cells via the PKC pathway." (PMID 39199574, 2024). "In glioma stem cells, inhibiting gp130 can attenuate IL-6-induced p-STAT3 expression, thereby inhibiting tumour growth." (PMID 38504172, 2024). "In glioma cell and human peripheral blood neutrophil cocultures, glioma cell–derived IL-6 and IL-8 extended neutrophil survival, suggesting that glioma cell–neutrophil interactions are reciprocal." (PMID 36594465, 2023). "In glioma, reactive astrocytes secrete protumor, antiinflammatory cytokines such as IL-6, TGF-β, and VEGF." (PMID 36647827, 2023). "TAMs also enhance the vascular mimicry of glioma by improving IL-6 secretion in glioma cells through the PKC pathway." (PMID 37012233, 2023). "Glioma-associated macrophages have been revealed to express several significant modulators that induce glioma growth and invasion, including IL-1β, TGF-β, IL-6, epidermal growth factor (EGF), and STI1, by modulating the perivascular GICs and glioma cells." (PMID 37012233, 2023). "Where IL-6 signaling is known to promote CSC phenotype in gliomas, vascular endothelial growth factor (VEGF) enhances tumorigenesis and cell proliferation." (PMID 36834653, 2023). "Increased release of IL6 promotes migration and invasion of glioma cells through the activation of the transcription factor STAT3." (PMID 38293652, 2023). "Cytokine networks in the glioma microenvironment include prostaglandins E2, IL-6, IL-10, and TGF-β, each of which inhibits T cell proliferation and activation." (PMID 37375698, 2023). "Expression of R-2-hydroxyglutarate impaired the differentiation and function of DCs in IDH-mutated gliomas and specifically suppressed MHC class I/II-mediated antigen cross-presentation and co-stimulation by IL-6." (PMID 38275375, 2023). "It is an independent prognostic factor in glioma patients, and its expression is significantly positively correlated with the IL6/JAK/STAT signalling pathway in glioma patients." (PMID 37452092, 2023). "Thereafter, it causes microglia to secrete more interleukin-6 (IL-6), which can result in binding glioma stem cells and their cell membrane receptors together, promoting the proliferation and growth of glioma stem cells through the IL-6/gp130/STAT3 pathway." (PMID 37280594, 2023). "On the other hand, the same study showed that in all the cytokines tested, it was the circulating IL-6 level (HR 1.10, 95%CI 1.05–1.16, p < 0.001) that was the most significantly correlated with poor overall survival in glioma patients." (PMID 38003396, 2023). "A previous study reported that elevated circulating levels of IL-6, IL-8, IL-17, TNF-α, TGF-β, and CRP are significantly linked to an increased risk of glioma." (PMID 38259287, 2023). "It has been shown that, compared to N-GDEVs, H-GDEVs contain higher levels of both IL-6 and miR-155-3p, and induce M2-like macrophage polarization via the IL-6-pSTAT3-miR-155-3p-autophagy-pSTAT3 positive feedback loop, promoting glioma progression." (PMID 38020906, 2023). "The NFAT1-mediated IL6/JAK-STAT signaling pathway has been observed to contribute to malignant progression in glioma patients." (PMID 37452092, 2023). "Differentiation of DCs is inhibited by cytokines secreted by glioma cells, such as IL‐10, IL‐6, prostaglandin E2 (PGE2) and VEGF." (PMID 36464889, 2023). "On the contrary, HOXC10 was positively associated with IL6/JAK/STAT3 and IL2/STAT5 signaling in glioma, and previous studies also indicated that these two signaling pathways were activated." (PMID 38154103, 2023). "In the first 24 h, glioma-neutrophil cultures produced high amounts of IL-8 and TNFα, slightly increased amounts of IL-12p70, and low to zero levels of IL-1β, IL-6, and IL-10." (PMID 37292196, 2023). "Other studies have also demonstrated that TAM-derived factors such as VEGF, EGF, bFGF, IL-1β and IL-6 are able to facilitate glioma vascularization." (PMID 37705736, 2023).